CTLA4 (cytotoxic T-lymphocyte associated protein 4)
Diseases named in the same sentence as CTLA4 in open-access papers (continued):
Sharing a sentence is not in itself a finding about the gene and the disease.
glioblastoma (continued). "al. reported improved efficacy upon combination of Ipilimumab (anti-CTLA-4 mAb) and Bevacizumab (anti-VEGF mAb) in glioblastoma patients." (PMID 37259163, 2023). "In previous studies, mice with glioblastoma (GBM) were subjected to treatment using anti-PD-1 antibody or combinational therapies using anti-PD-1 and anti-CTLA-4 antibodies." (PMID 38022677, 2023). "In addition to well-studied immune checkpoints such as PD-1/PD-L1 and CTLA-4, recent studies have highlighted the role of the CD200–CD200R axis in contributing to immunosuppression in glioblastoma." (PMID 40727443, 2025). "A Phase III trial (CheckMate 143) compared the efficacy of the PD-1 inhibitor nivolumab, either alone or in combination with the CTLA-4 inhibitor ipilimumab, versus the vascular endothelial growth factor (VEGF) inhibitor bevacizumab in a subset of patients with recurrent glioblastoma." (PMID 35406398, 2022). "Although there were several encouraging preclinical data on the use of immune checkpoint inhibitors (anti-PD-1 and anti-CTLA-4 antibodies, alone or in combination) for glioblastoma, clinical trials have been disappointing, with no patient survival improvement." (PMID 33572835, 2021). "Although preclinical trials with anti-PD1/PDL1 blockers (nivolumab/pembrolizumab) were not favourable, their use with an anti-CTLA4 blocker (ipilimumab) significantly prolonged the survival rate in glioblastoma." (PMID 35201470, 2021). "A phase I cohort of Checkmate 143 evaluated the safety, tolerability and clinical effects of nivolumab with or without ipilimumab (which targets CTLA-4) in recurrent glioblastoma patients." (PMID 30777100, 2019). "Single-agent treatment with CTLA-4 blocking antibody or dexamethasone did not produce a significant survival benefit compared to vehicle-treated animals in this well-established glioblastoma model." (PMID 29891009, 2018). "To determine whether the increased levels of PD-1+ CD8+ T-cells may be a negative modulator for SMC efficacy, we also assessed blocking the checkpoint target, PD-1, as well as CTLA-4, in combination with SMC using two mouse models of glioblastoma." (PMID 28198370, 2017). "However, many studies reported that the treatment of glioblastoma patients with anti-CTLA-4 or anti-PD-1 has no survival benefit compared to standard chemotherapy." (PMID 34728682, 2021). "However, in the case of glioblastoma, several studies reported that anti-CTLA-4 and/or anti-PD-1 antibodies exhibit no survival benefit compared to standard chemotherapy." (PMID 34305910, 2021). "Immune checkpoint blockade targeting PD-1 and CTLA-4 is an FDA-approved strategy in a number of solid tumors, yet has demonstrated limited success as a monotherapy in glioblastoma (GBM)." (PMID 32676514, 2020). "However, despite several reviews being published on other immune checkpoint molecules such as PD-1 and CTLA-4 in the glioblastoma setting, no such extensive review exists that specifically focuses on the role of TIM-3 in glioblastoma progression and immunosuppression." (PMID 40072074, 2025).
pneumonitis (92 papers, 2015 to 2025). An inflammatory process affecting the lung parenchyma. "Characteristics of included studies evaluating CTLA-4 inhibitors and associated pneumonitis adverse events." (PMID 40842533, 2025). "This meta-analysis indicates that CTLA-4 inhibitors are associated with a higher incidence of pneumonitis in NSCLC patients, particularly with tremelimumab." (PMID 40842533, 2025). "This meta-analysis demonstrates that the use of CTLA-4 inhibitors in NSCLC treatment is associated with a notable incidence of pneumonitis (4.0% for any-grade, 1.6% for high-grade)." (PMID 40842533, 2025). "Future research should focus on elucidating the underlying mechanisms of CTLA-4 inhibitor- induced pneumonitis, identifying predictive biomarkers for pneumonitis risk, and developing optimal prevention and management strategies." (PMID 40842533, 2025). "We further evaluated the risk of pneumonitis associated with different types of CTLA-4 inhibitors (tremelimumab and ipilimumab) in the treatment of NSCLC." (PMID 40842533, 2025). "Previous studies have shown that PD-1/PD-L1 inhibitors are generally associated with a higher incidence of pneumonitis compared to CTLA-4 inhibitors." (PMID 40842533, 2025). "For example, CTLA-4 agents are more likely to cause colitis and dermatitis than pneumonitis or thyroiditis." (PMID 40145913, 2025). "Retrospective analyses and meta-analyses have indicated that the risk of pneumonitis increases significantly when CTLA-4 inhibitors are combined with PD-1/PD-L1 blockade, suggesting a potential synergistic effect on immune-mediated lung toxicity." (PMID 40842533, 2025). "The incidence of ICI-associated pneumonitis in anti-PD-1/PD-L1 monotherapy and anti-CTLA-4/anti-PD-1 combination therapy is reported to be 2.5–5% and 7–10%, respectively." (PMID 39249163, 2024). "The overall incidence rate of pneumonitis varies from 2.5% to 5% with PD-1/PD-L1 inhibitors to 7%–10% with a dual combination of Cytotoxic T lymphocyte-associated antigen-4 (CTLA-4)/PD-1 inhibitors." (PMID 33194671, 2020). "Our meta-analysis showed that when combining ipilimumab (CTLA-4 inhibitors) with nivolumab (PD-1 inhibitors), the risk of all-grade pneumonitis (3.47 times), and severe pneumonitis (3.48 times) were higher than nivolumab or ipilimumab alone." (PMID 30778352, 2019). "When compared with CTLA-4 inhibitors, the risk of any grade pneumonitis induced by PD-1inhibitors seems higher, which however, was not statistically significant." (PMID 30778352, 2019). "The incidence of ICI pneumonitis ranges from 5% to 19%, being higher with programmed cell death protein 1 (PD-1) inhibitors than with programmed cell death ligand 1 (PD-L1) and cytotoxic T lymphocyte-associated protein 4 (CTLA-4) inhibitors." (PMID 40943893, 2025). "However, contrary to what was previously believed, for serious pneumonitis, we found a larger risk among patients treated with anti-CTLA-4 agents and ICI combinations, than with those treated with anti-PD-L1." (PMID 38372756, 2024). "The Society for Immunotherapy of Cancer's (SITC) Toxicity Management Working Group reports that targeted therapy of PD-1/PDL-1 and CTLA-4 is associated with pneumonitis in less than 5% of cases overall, with severe complications (grade three or higher) occurring in only 1-2% of patients." (PMID 38169638, 2024). "For example, CTLA-4 inhibitors are associated with higher rates of gastrointestinal effects and adrenal disorders, while PD-1/PD-L1 inhibitors are more associated with hypothyroidism and pneumonitis." (PMID 33019641, 2020). "Second, the risk of ICB‐related pneumonitis for each combined therapy (chemotherapy, targeted therapy, CTLA‐4 blockade or radiotherapy) might vary due to distinct pharmacological mechanisms." (PMID 29797416, 2018). "Moreover, the combination of anti-CTLA-4 and anti-PD-1 was likely to be associated with higher incidence of pneumonitis than anti-PD-1 monotherapy (6.88% vs. 2.92%, P < 0.001)." (PMID 28272463, 2017).
pneumonitis (continued). "Immune checkpoint inhibitors (ICIs), including anti-PD-1, anti-PD-L1, and anti-CTLA-4 antibodies, function by blocking inhibitory pathways to activate T cells, enabling tumor cell attack while increasing susceptibility to immune-related adverse events (irAEs) such as pneumonitis." (PMID 41312390, 2025). "In general, pneumonitis occurs more frequently in patients treated with PD-1 inhibitors, as compared to patients treated with PD-L1 inhibitors or with CTLA-4 inhibitors." (PMID 40145913, 2025). "One meta-analysis on clinical trials of ICI agents (PD-1, PD-L1, and CTLA-4) from 2003–2015 found that pneumonitis was more likely to occur in NSCLC and renal cell carcinoma as compared to melanoma." (PMID 40145913, 2025). "The results indicate that the overall incidence of pneumonitis (all grades) among NSCLC patients receiving CTLA-4 inhibitors was 4.0% [95% CI (2.2%, 5.8%)]." (PMID 40842533, 2025). "Although this meta-analysis evaluates pneumonitis in CTLA-4–based regimens, it remains challenging to attribute the observed pulmonary toxicity solely to CTLA-4 inhibition." (PMID 40842533, 2025). "In a comparison with a control group, patients receiving CTLA-4 inhibitors had a significantly higher incidence of any-grade pneumonitis [OR = 3.00, 95% CI (1.60, 5.64), p < 0.01]." (PMID 40842533, 2025). "The incidence of high-grade pneumonitis among NSCLC patients treated with CTLA-4 inhibitors was 1.6% ([95% CI (0.5%, 2.6%)]." (PMID 40842533, 2025). "This meta-analysis, which included 4,164 patients treated with CTLA-4 inhibitors (either as monotherapy or in combination therapy), found an overall incidence of any-grade pneumonitis of 4.0% [95% CI (2.2%, 5.8%)]." (PMID 40842533, 2025). "All nine studies included in this research reported the incidence of pneumonitis (all grades) in patients with NSCLC treated with CTLA-4 inhibitors." (PMID 40842533, 2025). "Patients treated with CTLA-4 inhibitors had a significantly higher incidence of any-grade pneumonitis [OR = 3.00, 95% CI (1.60, 5.64); p < 0.01]." (PMID 40842533, 2025). "The odds ratio (OR) was 3.00 [95% CI (1.60, 5.64); p < 0.01], indicating a significantly higher incidence of any-grade pneumonitis in patients treated with CTLA-4 inhibitors compared to the control group." (PMID 40842533, 2025). "Our analysis comparing the incidence of pneumonitis between patients receiving CTLA-4 inhibitors and control groups further supports the association between CTLA-4 inhibitors and pneumonitis." (PMID 40842533, 2025). "Additional studies to further confirm the detected association signal and to standardize guidelines for pneumonitis monitoring in ICI combination strategy should be conducted, particularly for anti-PD-1/CTLA-4 medications." (PMID 37124234, 2023). "We consistently found an increased reporting of pneumonitis toxicity for anti-PD-1/CTLA-4 plus chemotherapy compared with other anti-PD-1/CTLA-4 regimes in the two pharmacovigilance databases." (PMID 37124234, 2023). "CTLA4-Ig-treated mice, while being protected from the clinical measures used, still developed mild histological dermatitis, pneumonitis and pancreatitis, in some mice." (PMID 37156988, 2023). "Incidence of pneumonitis for PD-1/PD-L1 inhibitor monotherapy versus combination therapy with CTLA-4 inhibitor was 3% and 10%, respectively." (PMID 35453540, 2022). "Taken together, these data demonstrated that, upon anti-CTLA4 therapy, the LS diet reduced both pneumonitis and systemic irAE in breast-tumor-bearing mice." (PMID 35741331, 2022). "One patient received a combination of PD-1 and CTLA-4 antibody and developed pneumonitis 145 days after RT." (PMID 35740613, 2022). "The incidence of ICI-related pneumonitis was reported to be 2.5–5% with anti-PD-1/PD-L1 monotherapy and 7–10% with anti-CTLA-4/anti-PD-1 combination therapy." (PMID 34431319, 2021).
pneumonitis (continued). "Whilst our study also included PDL-1 and CTLA-4 related pneumonitis, making direct comparison difficult, this value is much lower than seen in our cohort." (PMID 34790682, 2021). "Interstitial lung irAEs, such as pneumonitis, happen in approximately 10% of patients taking combination therapy compared to3% in PD-1/CTLA-4 monotherapy, and therefore, need particular attention from a physician to examine respiratory symptoms." (PMID 32580338, 2020). "The overall incidence rate of ICI-related pneumonitis ranges from 2.5–5% with anti-PD-1/PD-L1 monotherapy to 7–10% with anti-CTLA-4/anti-PD-1 combination therapy." (PMID 32549075, 2020). "Pneumonitis as an immune-related adverse event (irAE) affects almost 5% of patients receiving anti-PD-1/PD-L1 in monotherapy and approximately 10% in anti-CTLA-4/anti-PD-1 combination therapy, rarely leading to death." (PMID 32900245, 2020). "This meta-analysis study provided new information to physicians regarding the difference of pneumonitis and pneumonia in cancer patients treated with ICIs, especially those with PD-1 and CTLA4 inhibitors." (PMID 30778352, 2019). "This study was conducted to determine the relative risk of pneumonitis and pneumonia in patients with solid tumor treated with PD-1/PDL-1inhibitor or CTLA4 inhibitor alone or in combination." (PMID 30778352, 2019). "Combination therapies with anti-CTLA-4/anti-PD-1/PD-L1 immunotherapy and with ICI/cytotoxic combinations also confer a higher risk of pneumonitis versus ICI monotherapy." (PMID 29162153, 2017). "The overall incidence of pneumonitis associated with PD-1/PDL-1 and CTLA-4-targeted therapies is <5%, with high-grade (≥grade 3) events occurring in 1–2% of patients." (PMID 29162153, 2017). "Anti-PD-1 mAB appears to be generally less toxic as compared to anti-CTLA4 mAB, with a slightly different toxicity profile such as pneumonitis." (PMID 26573233, 2015). "A comparison of pneumonitis incidence across different classes of ICIs may further highlight the clinical relevance of focusing on CTLA-4 inhibitors." (PMID 40842533, 2025). "In contrast, a retrospective study of 205 NSCLC patients found that 19% experienced pneumonitis during PD-1/PD-L1 blockade, suggesting that CTLA-4 inhibitors may result in a lower incidence of pneumonitis compared to PD-1/PD-L1 inhibitors." (PMID 40842533, 2025). "ICI pneumonitis is a rare condition (estimated incidence of 4% for anti-PD-1, 2% for anti-PD-L1, and <1% for anti-CTLA-4, reaching up to 10% with combination immunotherapy), but is potentially fatal, resulting from inflammation of the lung parenchyma secondary to the administration of these drugs." (PMID 40943893, 2025). "Additionally, 18 patients (1.50%) in the CTLA-4 inhibitor group developed high-grade pneumonitis, while 10 (0.85%) in the control group experienced high-grade pneumonitis." (PMID 40842533, 2025). "The higher incidence of pneumonitis in the CTLA-4 inhibitor group may be partly attributable to the additive pulmonary toxicity from combined treatments." (PMID 40842533, 2025). "Furthermore, the incidence of pneumonitis is higher when PD-1/PD-L1 inhibitors are used in combination with CTLA-4 inhibitors or sequential with chemotherapy, radiotherapy, or other immunotherapies than when used as a monotherapy." (PMID 39451777, 2024). "Other studies have found that combined CTLA-4 and PD-1 inhibitors could generate higher incidences of pneumonitis than either blockade individually." (PMID 37999142, 2023). "Agents acting on PD-1 axis are used in hemato-oncology more often than CTLA-4 inhibitors, so irAEs such as hyper/hypothyroidism or pneumonitis may occur more frequently." (PMID 34483944, 2021). "Similarly to CTLA-4, compared with men, women were more likely to develop all grades of PD-1-related toxicities (mainly including pneumonitis and endocrinopathies)." (PMID 33123120, 2020).
pneumonitis (continued). "Since the clinical application of ICIs, at least nine death cases related to ICI-induced pneumonitis (PD1/PD-L1: 7 cases; PD1 plus CTLA4: 2cases) and ten death cases of fatal pneumonia associated with ICIs (CTLA4: 7 cases; PD1/PD-L1: 3 cases) have been reported." (PMID 30778352, 2019). "In summary, our meta-analysis has demonstrated that PD-1/ PD-L1 inhibitors including nivolumab, pembrolizumab and atezolizumab could increase the risk of all-grade pneumonitis rather than CTLA4 inhibitor (ipilimumab)." (PMID 30778352, 2019). "CTLA4 inhibitor ipilimumab treatment alone could not increase the risk of pneumonitis but could augment the risk of pneumonitis in PD-1/PD-L1 inhibitor treated patients." (PMID 30778352, 2019). "Thus, the combined inhibitors of CTLA-4 and PD-1 could generate higher incidences of pneumonitis than either blockade." (PMID 30778352, 2019). "Our meta-analysis demonstrated that PD-1/ PD-L1 inhibitors including nivolumab, pembrolizumab, and Atezolizumab could increase the risk of all-grade pneumonitis, which was not seen in CTLA4 inhibitor (ipilimumab)." (PMID 30778352, 2019). "The incidence of any grades of ir-pneumonitis varies depending on therapy, with combined therapies having higher rates (6.5–10%) compared to anti-PD1, anti-PDL1, and anti-CTLA-4 monotherapies (4%, 2%, and <1%, respectively)." (PMID 39061225, 2024). "Active or untreated CNS metastases; history of pneumonitis, autoimmune or chronic viral diseases; previous treatment with docetaxel, CD137 agonists, anti-CTLA4, anti-PD L1, or anti-PD-1 therapeutic antibodies, or PD-1/PD-L1 pathway-targeting agents." (PMID 33761681, 2021). "Matching the finding from some current literature, where immune related hepatitis, pancreatitis, pneumonitis, and nephritis frequently recurred upon rechallenge with PD1 inhibitors in patients who previously experienced severe irAEs with dual PD-1 and CTLA-4 blockade." (PMID 41235221, 2025). "The risk ratio (RR) was 1.79 [95% CI (0.83, 3.85); P = 0.14], suggesting a higher incidence of high-grade pneumonitis in patients treated with CTLA-4 inhibitors, though the difference was not statistically significant." (PMID 40842533, 2025). "A comparison of pneumonitis incidence rates between patients who received CTLA-4 inhibitors and those who did not revealed that, out of 1,198 patients treated with CTLA-4 inhibitors, 38 (3.17%) experienced any-grade pneumonitis." (PMID 40842533, 2025). "Pneumonitis occurs in approximately 5% of patients receiving ICI therapy, can be life-threatening, and is less common in monotherapy with anti-PD-1/PD-L1 antibodies (3%) compared to combination therapy with anti-CTLA-4 antibodies (10%)." (PMID 39682118, 2024). "In clinical patients, although irAE such as arthritis and pneumonitis may occur with monotherapy, in animal model studies, anti-CTLA4 or anti-PD1 monotherapy cannot induce significant arthritis and pneumonitis, and the combination of the both is used to mimic the clinical manifestations." (PMID 36016934, 2022). "CTLA‐4 inhibitor treatment alone did not seem to increase the incidence of pneumonitis, but the incidence of CIP increased when CTLA‐4 inhibitor was combined with PD‐1/PD‐L1 inhibitor." (PMID 31762218, 2020).